FLT3 (fms related receptor tyrosine kinase 3)
Diseases named in the same sentence as FLT3 in open-access papers (continued):
Sharing a sentence is not in itself a finding about the gene and the disease.
leukemia (continued). "The different roles of FOXO genes in RUNX1 leukemia and FLT3-ITD leukemia highlights the mechanistic differences between the two leukemia subtypes and why treatment of both subtypes with the same drug may fail." (PMID 38007419, 2023). "Our findings revealed heterogeneous sorafenib sensitivity across different leukemia cell lines, with the highest resistance scores observed in U937, HL60, Jurkat, and FLT3-ITD mutation patients with sorafenib resistance and the lowest scores in MV4-11, MOLM13, K562, and THP-1." (PMID 37887047, 2023). "We conducted further investigations to determine whether FLT3-TAZ signaling is common in leukemia cells." (PMID 37932786, 2023). "Furthermore, we also collected AML primary cells from one FLT3-ITD AML patient (AML #5) and two FLT3-ITD AML relapsed patients to test the anti-leukemia effects of GNF-7." (PMID 38037057, 2023). "For example, FLT3-specific curcumin-loaded polymeric micelles with incorporated cytokine receptors and EVQ peptides can improve the directional effect of curcumin micelles on FLT3 leukemia cells and exhibit significant cytotoxicity and inhibition of leukemia cells with FLT3 targets." (PMID 37491290, 2023). "Since both FLT3–ITD and FLT3–TKD mutations promote constitutive FLT3 kinase activity, sustaining leukemic cell proliferation and survival, gilteritinib-mediated inhibitory effects have the potential to lessen the leukemia burden of AML patients." (PMID 37297842, 2023). "More precisely, targeting a single mutation (as tyrosine kinase inhibitors for BCR::ABL1 fusion gene, FLT3 or IDH1/2 mutations) is not the “magic bullet” since leukemia heterogeneity will allow tumor escape via clonal drift under chemotherapy pressure." (PMID 37444390, 2023). "In addition, GNF-7 shows strong anti-leukemia effects against AML cells harboring FLT3-ITD and FLT3-ITD/F691L in vitro." (PMID 38037057, 2023). "Sorafenib is a treatment strategy that has the potential to kill leukaemia blasts with FLT3/ITD." (PMID 37645444, 2023). "For example, curcumin (CM), which is insoluble with poor bioavailability, is extracted from the turmeric rhizome and has been proven to be effective against leukemia through the mechanism of cell cycle retardation and inhibitory effects in FLT3-overexpressing AML cells." (PMID 37491290, 2023). "The mutation of FLT3 genes may appear in every AML subgroup, especially NPM1mut AML (60%) and MLL-r leukemia (10%)." (PMID 37049787, 2023). "Nevertheless, FLT3-ITD accelerates leukaemia development in the CEBPAdm AML mouse model." (PMID 37019911, 2023). "When investigating the immunophenotype of FLT3-ITD driven leukemia, variability in myeloid marker expression could be detected." (PMID 37587260, 2023). "In the present study, we demonstrated that CG-806 has a superior anti-leukemia efficacy especially against AML harboring “gatekeeper” F691 mutations or FLT3 WT compared to other FLT3i, without detectable toxicity in normal BM samples." (PMID 36865133, 2023). "Indeed, pharmacological inhibition of Stat5 reduced leukemia burden in an in vivo FLT3-ITD + AML model." (PMID 37208719, 2023). "Furthermore, Midostaurin was reported to hamper leukemia development in BALB/c mice with FLT3-ITD- leukemia." (PMID 37438819, 2023). "The results of this study suggest that CG-806 is a promising multi-kinase inhibitor with anti-leukemia efficacy, regardless of FLT3 mutational status." (PMID 36865133, 2023). "Moreover, mutations in signaling pathway genes (e.g., FLT3, KIT, RAS) likely represent residual leukemia when detected, but being often sub-clonal, they have a low negative predictive value." (PMID 37444622, 2023).
leukemia (continued). "3.1.d—Mutation in NPM1, FLT3 and DNMT3A AML with three-way interaction among NPM1, DNMT3A and FLT3 occurs in around 6% of AML and is characterized by high leukemia stem cell (LSC) frequency, aberrant immunophenotype (with low CD34 and high CD56) and overexpression of hepatic leukemia factor (HLF)." (PMID 36831522, 2023). "Similarly, the combination of arsenic trioxide (1 and 2 μM) and sorafenib/quizartinib (4 and 8 nM) showed synergistic anti-leukemia effects in FLT3-ITD AML cells (MOLM14 and MV-4-11) and primary cells from patients." (PMID 37500645, 2023). "Our previous studies showed that ATO/ATRA combination can work synergistically to promote ubiquitination-mediated and autophagic degradation of FLT3-ITD protein, selectively kill FLT3-ITD leukemia cells, and reduce the leukemic burden in mice with FLT3-ITD leukemia." (PMID 38052803, 2023). "Previous studies showed that sitravatinib could significantly decrease AXL phosphorylation, which might also contribute to its efficacy against FLT3-ITD leukemia." (PMID 36691065, 2023). "Some PTK, such as FLT3, participate in immune suppression mediated by leukemia cells, which may promote the immune escape of leukemic clones." (PMID 36627892, 2022). "Moreover, WK2-16 effectively synergizes with quizartinib (AC220), a second-generation TKI, in FLT3-ITD+ AML to exhibit anti-leukemia effects in vitro and in vivo." (PMID 36231123, 2022). "In mouse models of NPM1-mutated/FLT3-ITD AML, venetoclax plus menin inhibitor was superior to the menin inhibitor alone, in eliminating leukemic cells (including leukemia stem/progenitor cells), decreasing Bcl-2 and Bcl-xL levels, and significantly prolonging mice OS." (PMID 36008542, 2022). "FLT3, CEPBA and NPM1 are commonly mutated genes in leukaemia." (PMID 36286062, 2022). "But at least in ZNF384-r ALL, there seems to be a dependency of FLT3 signaling although its exact contribution to leukemogenesis and leukemia maintenance remains unclear." (PMID 36104354, 2022). "Based on that, we verified that patient’s cells harboring FLT3 mutations, a frequent secondary event in KMT2A-r leukemia, showed higher sensitivity to Foretinib, suggesting that this drug might turn into a therapeutic option for these subgroups." (PMID 35734412, 2022). "Thus, we demonstrated that VRP-FLT3 vaccine is capable of inducing a prompt IgG antibody response to FLT3 in both our lymphoma and leukemia mouse models." (PMID 35686131, 2022). "Accordingly, CDDD11-8 inhibited the proliferation of leukemia cell lines with FLT3-ITD and MLL fusions (MV4-11 and MOLM-13 cells) more potently relative to cell lines lacking these mutations (e.g., U937) or those harboring either one of these genetic aberrations (e.g., PL21 and THP-1)." (PMID 35267421, 2022). "This led to the hypothesis that FLT3-ITD inhibition might result in leukemia cell detachment from the bone marrow niche through PTK2B inhibition." (PMID 36056084, 2022). "In our study, FLT3 inhibitor resistant leukemia cells showed significantly activating autophagy." (PMID 35794565, 2022). "This also suggests that DOCK2 may regulate the growth of FLT3-ITD leukemia cells through both MMR and DDR molecular mechanisms." (PMID 36250020, 2022). "The data indicate that HEHDS-guided therapy may be able to improve CR in leukemia patients significantly, especially in FLT3-ITD AML patients." (PMID 35845130, 2022). "Furthermore, we demonstrated an enhanced leukaemia suppression of an AML cell line xenograft model using FLT3‐ITD ASO loaded CD33‐targeting RBCEVs and in patient‐derived xenograft models of AML using miR‐125b ASO loaded CD33‐targeting RBCEVs." (PMID 35851970, 2022). "As of the last follow-up on day +181, she has no active infections, has no acute or chronic GVHD, and remains in leukemia remission (FLT3 ITD mutation analysis from peripheral blood negative as of day +177) with 100% Lansky performance status." (PMID 35955881, 2022).
leukemia (continued). "In such a context, upregulated RUNX1 cooperates with FLT3‐ITD to induce leukaemia." (PMID 36467848, 2022). "Our data further supports that autophagy significantly involves in leukemia progression and resistance, could be a promising therapeutic target in FLT3-ITD-positive AML." (PMID 35794565, 2022). "FLT3 inhibitor resistance is the important reason for leukemia relapse in FLT3-ITD-positive AML." (PMID 35794565, 2022). "As expected, genes associated with AML proliferation (FLT3, KIT), leukemia stem cells (CD34, CD38, and IL1RAP), and candidate genes overexpressed in AML (CD99, CD200, and LAMP2) were downregulated after chemotherapy, consistent with recent scRNA-Seq and immunohistochemistry data." (PMID 36099049, 2022). "FLT3-ITD leukemia cells showed significantly different therapeutic responses to Ara-C and 5-FU." (PMID 36250020, 2022). "DBPR114 potently inhibited the growth of FLT3-variant AML cells but was minimally effective against FLT3-negative leukemia cell lines." (PMID 35062934, 2022). "It is important to note that ATM-mediated regulation of mTOR protein levels does not appear to be unique to FLT3-dependent AMLs or leukemia in general, as implicated with our analyses of other cell types." (PMID 36259537, 2022). "Resistance to FLT3 inhibitors plays an important role in leukemia relapse." (PMID 35794565, 2022). "In addition, SIRT1 is activated by the c-MYC oncogenic network in human FLT3-ITD+ AML leukemia stem cells (LSCs), which contributes to their maintenance and drug resistance." (PMID 35656547, 2022). "Moreover, our therapeutic studies in mice demonstrated the limitation of FLT3-targeted monotherapy in eliminating leukemia from the BM compared to the periphery (spleen and blood), leading to relapse even with sustained treatment." (PMID 36259537, 2022). "Based on these studies, the Acute Leukemia Working Party of the European Society for Blood and Marrow Transplantation recommends post-transplant maintenance therapy with a FLT3 inhibitor, preferably sorafenib, for patients who undergo allo-HCT for FLT3-ITD-mutated AML." (PMID 35460465, 2022). "Moreover, ACS reduced cell viability of primary AML samples carrying FLT3 or RAS mutations and accentuated the leukemia inhibitory and apoptotic effects of quizartinib, ibrutinib, and doxorubicin." (PMID 35624145, 2022). "Internal tandem duplication (ITD) mutation in the Fms-like tyrosine kinase 3 gene (FLT3/ITD) causes a significant increase in aerobic glycolysis through AKT-mediated upregulation of mitochondrial hexokinase 2 (HK2) and renders leukemia cells highly dependent on glycolysis." (PMID 35912231, 2022). "Inhibition of autophagy or ATF4 enhances the anti-leukemia effect of FLT3 inhibitors." (PMID 35794565, 2022). "This review provides an overview on the established and evolving use of FLT3 inhibitors to prevent or treat relapse of AML in the context of allo-HCT, focusing on the recently discovered immunogenic potential of some FLT3 inhibitors and addressing the possible mechanisms of leukemia drug-escape." (PMID 35460465, 2022). "Of the genes more highly expressed in female FLT3‐ITD‐positive AML, the hedgehog signalling mediator GLI2 has been associated with FLT3‐ITD‐mutated leukaemia, while HOXB‐AS3 is reportedly upregulated in NPM1‐mutated AML, and has been implied to contribute in regulation of AML cell‐cycle progression." (PMID 34101344, 2021). "Collectively, these data suggest that FLT3-ITD may represent an important pathway through which DOT1L inhibition reduces leukemia cell survival." (PMID 34263728, 2021). "We postulate that inhibition of FLT3 by LT-171-861 at such a low concentration as used in our study may be important for leukemia treatment." (PMID 33391463, 2021).
leukemia (continued). "Notably, sorafenib has been shown to increase IL-15 production in mutant FLT3-ITD leukemia cells, increase IFN-γ production, and lead to metabolic reprograming of leukemia reactive T cells among relapsed patients post-allo-HCT who respond to treatment." (PMID 34976845, 2021). "In addition, leukemia stem cells (LSCs) and drug resistance (FLT3 inhibitors, BCL2 inhibitors etc.)are still difficult problems for the treatment of AML." (PMID 34454635, 2021). "In conclusion, this study demonstrates that combined treatment with a FLT3 TKI and BCL-2i synergistically inhibits proliferation and induces apoptosis/cell death of FLT3/ITD leukemia cell lines and primary FLT3/ITD AML patient samples, both in vitro and in vivo." (PMID 34024909, 2021). "Through the analysis of transcriptomic data of 701 leukemia and NB patient samples and cell lines, we revealed that the expression of RTK, such as KIT, FLT3, AXL, FGFR3, and NTRK1, is linked with HDAC class I. Although HDAC inhibitors have antitumor activity, they also have high whole-body toxicity." (PMID 34944663, 2021). "Finally, in leukemia cells from two R/R FLT3 mutant patients clinically resistant to TKIs, whose cells were resistant to gilteritinib in vitro, treatment with OTS167 was capable of inducing cell death." (PMID 33658483, 2021). "The distinctive HDAC SCORE and expression were specific for FLT3 (leukemia) and NTRK1 (NB)." (PMID 34944663, 2021). "The FLT3-mutation like pattern was enriched in NPM1 and DNMT3A mutant leukemias." (PMID 33592069, 2021). "However, overexpression of FLT3, characteristic of this subtype, makes this leukemia amenable to FLT3 inhibition." (PMID 34501239, 2021). "Of note, as emphasized in the adult ELN 2017 risk classification, FLT3-ITD mutations should not be used as adverse prognostic markers if they occur within favorable cytogenetic risk groups such as CBF leukemia." (PMID 34204358, 2021). "Using next‐generation sequencing, a FLT3‐ITD variant allele frequency of ≤10−4 was used to define FLT3‐ITD clearance in patients with no morphologic leukemia (ie, CRc)." (PMID 33340276, 2021). "It is possible that the dependence of MLL-r, FLT3-ITD+ leukemia on FLT3-ITD expression may be due to HOXA9 requiring STAT5A and/or PBX3 and C/EBPA to cooperatively bind select target genes." (PMID 34263728, 2021). "In addition to its anti-FLT3 activity, sorafenib has been shown to induce interleukin-15 production by FLT3-positive leukemia cells, thereby activating the donor CD8+ T cells and promoting the GVL effect." (PMID 35047405, 2021). "The screening identified ABT-737, a B-cell lymphoma (BCL)-family inhibitor and Purvalanol A, a CDK2 inhibitor, as a combination with therapeutic potential for MLL-rearranged leukemia and internal tandem duplications of the fms-related tyrosine kinase 3 gene (FLT3-ITD)." (PMID 34594227, 2021). "FLT3-ITD with additional NPM1 mutation, AML1-ETO fusion gene, NUP98 fusion, CBFβ-SMMHC fusion gene, and TET2 deletion can cause leukemia." (PMID 33836835, 2021). "However, the majority of FLT3-TKD and NRAS mutations presented in the primary leukemia were loss at relapse." (PMID 33577442, 2021). "Whether the benefits of FLT3 inhibitor post HSCT are related to its suppressive effects on residual FLT3-ITD AML cells or potentiation on graft-versus-leukaemia effects would have to be further evaluated." (PMID 32102366, 2020). "However, despite the curative potential of FLT3-CAR T-cell-based immunotherapies based on the graft-versus-leukaemia effect, severe side-effects have to be considered." (PMID 33003568, 2020). "Furthermore, our studies show that SYK suppression potentiates the anti‐leukaemic activity of FLT3 inhibition in cell line‐based models of mutant CBL‐positive leukaemia." (PMID 31943762, 2020).
leukemia (continued). "FLT3 and JAK3 mutations, although less frequent in CBF leukemia, but may result in sensitivity to inhibition by kinase inhibitors such as midastaurin, quizartinib or ruxolitinib, which, however, remains to be clinically investigated." (PMID 33322186, 2020). "Importantly, serum FST positively correlated with leukemia engraftment in FLT3/ITD AML patient‐derived xenograft mice and leukemia blast percentage in primary AML patients." (PMID 32134197, 2020). "In addition, the inability of FLT3 TKIs to eliminate leukemia stem cells also contributes to treatment failure." (PMID 32393312, 2020). "The mechanisms are heterogeneous and may involve emergence of clones that are resistant to FLT3 inhibitors being used; protection of leukaemia cells by BM microenvironment; and adaptation of leukaemia cells to survive FLT3 inhibitors." (PMID 32102366, 2020). "There was one leukemia recurrence in FLT3 MRD(−)/NPM(−) group." (PMID 32333156, 2020). "Also, immunofluorescence of LAMP1 similarly a diffused cellular distribution of lysosomes in cell lines from leukemia (MV‐4‐11), bladder (J82), and NSCLC (H1781) cancers with FLT3, FGFR, and Her2 tyrosine kinase mutations, respectively." (PMID 32194831, 2020). "Currently, long-term cure is achieved in only 60% of pediatric AML cases and the possibility of relapse is still high, ranging between 25% and 35%, especially for poor prognosis AML subtypes including FMS-like tyrosine kinase 3 (FLT3) mutated and mixed lineage leukemia rearranged (MLL-r)." (PMID 32698374, 2020). "In this study, we evaluated the effects of ULK1 inhibition on leukemia cell death in FLT3-ITD AML." (PMID 32393312, 2020). "Therefore, it would be expected that targeted inhibitors of FLT3 would be an effective therapy for CBL mutant‐driven leukaemia as well as for mutant FLT3‐positive leukaemia." (PMID 31943762, 2020). "Reports have demonstrated that silencing survivin could significantly reduce the proliferation of leukemia cells and induce apoptosis in FLT3 mutant mice 24-26." (PMID 33123268, 2020). "However, midostaurin was identified as a potential confounder as it was part of the treatment for Flt3-mutated AML in most patients and have been shown to induce Mk differentiation in human leukemia cells." (PMID 33363015, 2020). "Similar niche for AML may exist and protect leukaemia cells from the inhibitory effects of FLT3 inhibitors." (PMID 32102366, 2020). "In children, midostaurin has been investigated as monotherapy in r/r pediatric leukemia, including KMT2A-rearranged ALL or FLT3-mutated AML (NCT0866281), which unfortunately demonstrated limited efficacy in the 22 enrolled participants (the trial terminated early due to lack of enrollment)." (PMID 32050659, 2020). "ULK1 inhibition also induced cell death, albeit to a lesser degree, in FLT3-WT leukemia cells, necessitating a clarification of whether the apoptosis-inducing effects of ULK1 inhibition were primarily due to ULK1 inhibition or off-target effects thereof." (PMID 32393312, 2020). "We compared the protein expression level of p-STAT5/STAT5, Pim-1 and CXCR4 among the FLT3-ITD-mutated, FLT3-wt and normal control groups using Western blotting to further examine whether CXCR4 expression in leukemia cells is regulated by FLT3-ITD mutations." (PMID 31434952, 2019). "The prognostic impact of PD-L1 in FLT3-ITD AML could thus also be due to an increased resistance of leukemia cells to chemotherapy." (PMID 31185600, 2019). "In addition, we observed that chronic treatment with sorafenib resulted in an increased oxidative stress in FLT3/ITD-positive leukemia cells, which was accompanied by decreased cell proliferation and an enhanced antioxidant response." (PMID 30947742, 2019). "Indeed, CXCR4 overexpression is associated with extramedullary infiltration in many hematological malignancies, and our study indicated that the FLT3-ITD MR was positively correlated with the RFI for CXCR4 expression on leukemia cells." (PMID 31434952, 2019).